PRDM15 (PR/SET domain 15)
Diseases named in the same sentence as PRDM15 in open-access papers:
PRDM15 is named in the same sentence as 32 diseases in open-access papers, as found by Europe PMC text mining. Sharing a sentence is not in itself a finding about the gene and the disease. The quoted sentences say what the papers report.
B cell lymphomas (5 papers, 2020 to 2025). "Altogether, these results are consistent with a model whereby loss of PRDM15 in B-cell lymphomas results in a transcriptional downregulation of key metabolic genes causing a metabolic crisis which then leads to cell death." (PMID 32665551, 2020). "Collectively, these results indicate that the loss of PRDM15 has a profound impact on the B-cell lymphoma metabolome, which matches its effects on the transcriptome." (PMID 32665551, 2020). "Interestingly, CUX1 expression is also decreased in PRDM15-deficient B cell lymphoma models, where loss of PRDM15 impairs lymphomagenesis." (PMID 41282092, 2025). "While studies have shown that PRDM15 is overexpressed in B-cell lymphomas and colon adenocarcinoma and contributes to tumorigenesis and radioresistance, it remains unknow whether PRDM15 is implicated in CCA." (PMID 37817227, 2023). "Collectively, our data demonstrate that PRDM15 fuels the metabolic requirement of B-cell lymphomas and validate it as an attractive and previously unrecognized target in oncology." (PMID 32665551, 2020). "The PRDM15 gene is of particular interest, given its low expression in adult tissues and its overexpression in B-cell lymphomas." (PMID 32665551, 2020). "Staining of a B-cell lymphoma-tissue microarray (TMA) confirmed elevated levels of PRDM15, and nuclear localization, in FL, DLBCL, BL, small lymphocytic-lymphomas (SLL) and mantel cell-lymphomas (MCL), compared to normal tonsil controls." (PMID 32665551, 2020). "The transcriptional regulator PRDM15 is expressed at low levels in normal tissues but overexpressed in B-cell lymphomas." (PMID 32665551, 2020). "To conclude, we here uncover a PRDM15-driven transcriptional program, pertinent to the high energy demands of B-cell lymphomas." (PMID 32665551, 2020). "Herein, we demonstrate that PRDM15 is upregulated not only in FL, but in the majority of B-cell lymphomas." (PMID 32665551, 2020). "Depletion of PRDM15, genetically or using antisense drugs, impairs tumor growth and induces specific killing of B-cell lymphomas, both in vitro and in vivo." (PMID 32665551, 2020). "More importantly, our protein expression analysis and in vivo functional assays support a wide therapeutic window and suggest that PRDM15 would be an excellent target for B-cell lymphoma treatment." (PMID 32665551, 2020). "PRDM15 has been suggested as a good target for B cell lymphoma treatment." (PMID 36674842, 2023). "PRDM15 depletion increases specificity in killing B cell lymphomas." (PMID 36674842, 2023). "Interestingly, out of 16 tumors isolated from TAM-injected mice, only 5 were B-cell lymphomas (B220+), out of which 4 were escapees (2 expressed PRDM15 in the nucleus, 2 expressed PRDM15 in the cytoplasm) and only one had undetectable levels of PRDM15." (PMID 32665551, 2020). "Collectively, these findings suggest that PRDM15 may play a major role in B-cell lymphoma maintenance." (PMID 32665551, 2020). "Collectively, these data demonstrate that PRDM15 acts as a master regulator controlling the transcription of key metabolic enzymes and regulators, to fuel B-cell lymphomagenesis, and validate it as a promising and hitherto unrecognized target for the treatment of B-cell lymphomas." (PMID 32665551, 2020). "In B cell lymphomas, PRDM15 is required to rewire their metabolism by regulating the mTOR/PI3K pathway, and targeted PRDM15 depletion in lymphoma cells results in tumor regression." (PMID 41282092, 2025). "The latest progress shows that PRDM15 regulates the transcription programs that involve the PI3K/AKT/mTOR pathway and glycolysis in B-cell lymphomas." (PMID 36674842, 2023). "These transgenic mice develop B-cell lymphomas driven by MYC, whereby PRDM15 can be conditionally deleted at various stages of tumor development." (PMID 32665551, 2020). "Mechanistically, PRDM15 regulates a transcriptional program that sustains the activity of the PI3K/AKT/mTOR pathway and glycolysis in B-cell lymphomas." (PMID 32665551, 2020).
B cell lymphomas (continued). "In contrast, PRDM15 depletion alone attenuated mTORC1 signaling without activation of these compensatory pathways, consistent with the almost complete eradication of B-cell lymphomas observed in vivo." (PMID 32665551, 2020).
lymphoma (4 papers, 2020 to 2025). A malignant (clonal) proliferation of B- lymphocytes or T- lymphocytes which involves the lymph nodes, bone marrow and/or extranodal sites. "In order to block the functions of PRDM15 in a pathological context and develop a precision therapy for lymphoma and leukemia, mutations, variants, and other genetic polymorphisms of PRDM15 will be investigated." (PMID 36674842, 2023). "Acute depletion of PRDM15 by addition of 4-OHT to cell culture media resulted in a severe growth delay of the lymphoma cells, which was rescued by exogenous expression of PRDM15 in the Prdm15Δ/Δ cells, confirming that this phenotype is caused by PRDM15 loss." (PMID 32665551, 2020). "Consistent with this, PRDM15 has been proposed to be an excellent target for lymphoma therapy and a novel strategy for therapeutic intervention to selectively kill PRDM15-overexpressing tumors." (PMID 36674842, 2023). "Taken together, there is an unmet need to identify the functions of PRDM15 for therapeutic intervention across a wide range of aggressive lymphomas." (PMID 36674842, 2023). "The effects of both linsitinib and everolimus on cell viability mirrored those observed upon PRDM15 abrogation, as we observed a clear correlation between the sensitivity of primary mouse lymphoma cells and PRDM15 status in the cell for each drug." (PMID 32665551, 2020). "PRDM15 is highly expressed, but rarely mutated, in FL24, DLBCL and Burkitt’s lymphomas (BL) and in B-cell-derived lymphoma cell lines (i.e. Burkitt’s, DLBCL, B-ALL, etc.)." (PMID 32665551, 2020). "To corroborate the cell autonomous function of PRDM15 in lymphoma cells, we additionally transplanted Eμ-Myc lymphomas in WT or PRDM15 KO recipient mice (Prdm15F/F; CreER treated with IP TAM injections)." (PMID 32665551, 2020). "In lymphoma cells, PRDM15 regulates the transcription of key genes involved in two major metabolic axes required for tumor cell survival: PI3K/AKT/mTOR signaling (InsR and Igf1R) and glycolysis (e.g Pkm, Pfkp, Eno3)." (PMID 32665551, 2020). "We therefore determined the binding repertoire of PRDM15 in tumoral Eμ-Myc lymphoma cells by performing chromatin immunoprecipitation, followed by next generation sequencing (ChIP-seq) and identified 1327 PRDM15 target sites." (PMID 32665551, 2020). "The relevance of these additional targets, as well as potential mechanisms of how PRDM15 controls uptake and/or utilization of glutamine in the context of lymphoma warrants further investigations." (PMID 32665551, 2020). "Next, to validate downregulation of the PI3K/AKT/mTOR pathway in Eμ-Myc lymphomas upon PRDM15 depletion, we starved WT and KO cells overnight and subsequently stimulated them with insulin and IGF1." (PMID 32665551, 2020). "Antisense oligonucleotide (AON)-mediated depletion of PRDM15 impairs tumor growth in a lymphoma PDX model." (PMID 32665551, 2020). "In addition, PRDM15 is overexpressed in immune cells and follicular lymphoma and is critical for maintenance of human lymphomas and embryonic development." (PMID 36674842, 2023). "By exploring the ongoing DepMap project (22Q2), we have found that PRDM15 is overexpressed in almost all cancer cell lines, particularly in lymphoma cell lines and multiple myeloma cancer lines which display relatively higher dependence on PRDM15 compared to other cancer lines." (PMID 36674842, 2023). "Of the 579 overrepresented proteins, six proteins were found in at least 20-fold higher abundance in lymphoma patients (NUCKS1, SLC14A1, GPALPP1, ADPRH, CD72, PRDM15)." (PMID 33562532, 2021).
diffuse large B-cell lymphoma (3 papers, 2020 to 2023). "PRDM15 could be a key regulator in diffuse large B-cell lymphoma (DLBCL), which sustained the activity of the PI3K/AKT/mTOR pathway and glycolysis." (PMID 36982660, 2023).
holoprosencephaly (3 papers, 2023 to 2025). Holoprosencephaly (HPE) is a complex brain malformation resulting from incomplete cleavage of the prosencephalon, occurring between the 18th and 28th day of gestation, and affecting both the forebrain and face, which results in neurological manifestations and facial anomalies of variable severity. "Mutations in PRDM15 lead to a syndromic form of holoprosencephaly (HPE) known as the Galloway–Mowat syndrome (GAMOS)." (PMID 38444828, 2024).
brain malformations (2 papers, 2022 to 2024). "Previous studies have shown that Prdm15 loss of function also leads to brain malformations." (PMID 38444828, 2024). "A loss-of-function (LOF) mutation (C844Y) in PRDM15, which regulates NOTCH and WNT signaling pathways, was identified in patients with brain malformations." (PMID 35456240, 2022).
cholangiocarcinoma (2 papers, 2023 to 2025). A carcinoma that arises from the intrahepatic biliary tree (intrahepatic cholangiocarcinoma) or from the junction, or adjacent to the junction, of the right and left hepatic ducts (hilar cholangiocarcinoma). "In cholangiocarcinoma (CCA), METTL16 targets PRDM15 to regulate FGFR4 expression, promoting cell proliferation and malignant progression." (PMID 41256854, 2025).
colon adenocarcinoma (2 papers, 2022 to 2023). "PRDM15 expression in colon adenocarcinoma was higher than that in normal tissues." (PMID 36402747, 2022).
colorectal cancer (2 papers, 2022 to 2023). A primary or metastatic malignant neoplasm that affects the colon or rectum. "Bioinformatical analysis from the TCGA database also showed that PRDM15 was associated with colorectal cancer." (PMID 36402747, 2022). "The goal of this study was to explore the role of PRDM15 involved in the radioresistance of colorectal cancer and to clarify the underlying mechanism." (PMID 36402747, 2022). "Knockdown of PRDM15 inhibited DNA damage repair and increased radiosensitivity in colorectal cancer cells." (PMID 36402747, 2022). "In this study, we confirmed that knockdown of PRDM15 promotes DNA damage in colorectal cancer cells and induces apoptosis." (PMID 36402747, 2022). "Our findings revealed that inhibiting PRDM15 was potent to overcome radioresistance through abrogating DNA repair in colorectal cancer cells." (PMID 36402747, 2022). "In the present study, we reported that PRDM15 confers radioresistance of colorectal cancer through facilitating NHEJ repair machinery." (PMID 36402747, 2022). "For instance, our investigation has revealed that PR domain zinc finger protein 15 (PRDM15) may contribute to the development of radiotherapy resistance in colorectal cancer, but the implementation of subsequent studies targeting it with inhibitors is confronted with numerous challenges." (PMID 38115743, 2023).
lung carcinoma (2 papers, 2014 to 2023). "For example, three colon cancer tissues were separated from the others and grouped together with lung cancers, showing hypermethylation in the VHL and PRDM15." (PMID 24842468, 2014).
aniridia (1 paper, 2024). Aniridia is a congenital ocular malformation characterized by the complete or partial absence of the iris. "Consistent with our findings upon Prdm15 KD, PAX6 gene mutations in humans are associated with eye defects such as aniridia and corneal opacification or cataract." (PMID 38444828, 2024).
Autoimmunity (1 paper, 2020). The occurrence of an immune reaction against the organism's own cells or tissues. "It is also noteworthy that both PRDM15 and PPP1R12B have been related to immune dysfunction and/or autoimmunity, mechanisms that are thought to play a key role in COPD pathogenesis." (PMID 32824824, 2020). "Hence, PRDM15 is overexpressed in B-cell dysregulation, a characteristic feature of COPD, whereas PPP1R12B and its “M20” transcript are higher in patients with celiac disease autoimmunity." (PMID 32824824, 2020).
coloboma (1 paper, 2024). An abnormality in which a part of a structure in one or both eyes is missing. "Comparing the two PRDM15 mutation variants, the embryos rescued with hPRDM15-C844Y RNA tended to have smaller eyes and more coloboma than the embryos rescued with the hPRDM15-M154K variant, supporting the C884Y variant as more pathogenic in the anterior neural development." (PMID 38444828, 2024). "We, therefore, quantitatively measured the eye size and showed a significantly smaller eye area upon Prdm15 depletion describing a strong microphthalmia phenotype and a coloboma phenotype, consistent with the ocular defects in patients with HPE or GAMOS." (PMID 38444828, 2024).
hearts defects (1 paper, 2024). "However, a study of DS individuals found that congenital hearts defects were associated with two short copy number variants located between RIPK4 and PRDM15 and within ZBTB21 respectively, implicating this region in DS-CHD." (PMID 38266108, 2024).
Hepatic failure (1 paper, 2023). "On the other hand, liver cirrhosis, fatty liver, and hepatic failure phenotypes were associated with variants in NAB1, CALD1, ZBTB16, GAN, TEMD3, and/or PRDM15 genes." (PMID 37664632, 2023).
ovary cancer (1 paper, 2023). "An exemplary analysis of the two PRDM15 co-dependency genes MNT and RALGDs revealed that it is correlated with MNT in both ovary cancer cell lines and blood cancer cell lines and negatively correlated with TSC22D1 in blood cancer cell lines." (PMID 36674842, 2023).
rectal cancer (1 paper, 2022). A primary or metastatic malignant neoplasm that affects the rectum. "Moreover, PRDM15 upregulation was associated with inferior tumor regression and poor prognosis in locally advanced rectal cancer patients treated with neoadjuvant chemoradiotherapy." (PMID 36402747, 2022). "Furthermore, a higher expression of PRDM15 was found to be associated with poorer prognosis in locally advanced rectal cancer patients treated with neoadjuvant chemoradiotherapy." (PMID 36402747, 2022). "Moreover, CPT is commonly used in clinical treatment in rectal cancer, which further proves that PRDM15 is associated with poor clinical prognosis, and also confirms that PRDM15 could also be a potential target for the combined treatment with CPT." (PMID 36402747, 2022). "Indeed, locally advanced rectal cancer patients with lower PRDM15 expression were more likely to acquire better tumor regression and survival outcomes." (PMID 36402747, 2022). "And targeting PRDM15 could be a potential strategy for improving the radiotherapy effects in radioresistant rectal cancer patients." (PMID 36402747, 2022). "These in vivo experiments confirmed that PRDM15 could be a potent target of radiosensitization in rectal cancer." (PMID 36402747, 2022). "Therefore, PRDM15 might serve as an effective predictive biomarker of radiosensitivity and a target for radiosensitization in locally advanced rectal cancer patients; these findings may contribute to the precise treatment strategies in clinical practice in the future." (PMID 36402747, 2022).
cancer (9 papers, 2018 to 2025). A tumor composed of atypical neoplastic, often pleomorphic cells that invade other tissues. "In detail, PRDM8 and PRDM15 were mutated at low rates in most of the analyzed cancer types except PAAD where they were both frequently mutated (16.0% and 11.2%, respectively)." (PMID 30347759, 2018). "PRDM15 has recently been shown to be highly expressed in multiple cancer types and more specifically in B cell malignancies." (PMID 36674842, 2023). "While PRDM15 has been shown to play a role in stem cell biology and during early development, its role in cancer biology remains undefined." (PMID 37817227, 2023). "Despite its characterized role in stem cell biology and during early development, the role of PRDM15 in cancer remains obscure." (PMID 36402747, 2022). "The results showed that at 0.5 h after 8 Gy IR, the expression level of PRDM15 in cancer cells increased markedly at 0.5 h after IR and was decreased at 12 h." (PMID 36402747, 2022). "We then generated the PDX model, and we injected the PRDM15-KD and PRDM15-NC lentivirus directly into the cancer tissues." (PMID 36402747, 2022). "We found that the expression level of PRDM15 in TRG3 cancer tissues was significantly higher than that in tissues from TRG 0-2 group." (PMID 36402747, 2022). "Knockdown of PRDM15 in cancer cells or patient tissues derived xenograft increased the efficacy of radiotherapy." (PMID 36402747, 2022). "Intrigued by this observation, we first assessed the expression of PRDM15 mRNA across cancer cell lines and patient samples." (PMID 32665551, 2020). "Despite its well characterized role in stem cell biology and during early development, the role of PRDM15 in cancer remains obscure." (PMID 32665551, 2020). "Heterogeneity in the mutation frequencies was observed in the different tumor types with higher mutation rates found for PRDM3/MECOM, PRDM8, PRDM9, PRDM15, ZFPM1/FOG1 and ZFPM2/FOG2 in specific cancers." (PMID 30347759, 2018). "However, the exact role of PRDM15 in DNA damage response and cancer therapy remains to be investigated further." (PMID 36402747, 2022). "Notwithstanding that it was recently reported that PRDM15 is highly expressed in immune cells and overexpressed in FL24, its function in cancer remains largely undocumented." (PMID 32665551, 2020). "PRDM15 is a member of the PRDF1 and RIZ1 homology domain-containing (PRDM) proteins which are sequence-specific transcriptional regulators involved in cell stemness and development, often dysregulated in cancer." (PMID 37817227, 2023). "Indeed, this is what we observe in the in vivo mouse models where we have a substantial delay in lymphomagenesis, and mice succumb rarely to B-cell tumors (when tumors escape Prdm15 deletion), but rather to late onset T and non-B/T malignancies." (PMID 32665551, 2020).
tumor (5 papers, 2018 to 2025). "It was found that in the PRDM15-KD group, radiation-induced apoptosis of tumor cells was greatly increased." (PMID 36402747, 2022). "In this study, we firstly used CDX model, and found that tumors derived from PRDM15-KD cells are more sensitive to radiotherapy than tumor derived from PRDM15-NC cells." (PMID 36402747, 2022). "Similar to the data of CDX, PRDM15-KD group eventually grew slower than the irradiated PRDM15-NC group, largely due to the more profound effect of radiation on tumor suppression." (PMID 36402747, 2022). "Next, to assess the role of PRDM15 in tumor maintenance, primary tumors were isolated from tumor-bearing PRDM15F/F;CreER;Eμ-Myc mice and transplanted into syngeneic recipient mice." (PMID 32665551, 2020). "This suggests that knocking down PRDM15 can increase the degree of tumor damage after IR." (PMID 36402747, 2022). "Tumor growth was most rapid in the PRDM15-NC group without any intervention, and most inhibited in the PRDM15-KD group plus IR." (PMID 36402747, 2022).
hematological tumors (1 paper, 2023). "Among them, HPRT1, TSC22D1, and COX16 have significantly correlated dependence profiles (p < 0.05) with PRDM15 in lymphocyte or blood cancer cell lines from these pathways." (PMID 36674842, 2023).
PRDM15 also shares sentences with these, for which no sentence is quoted: Down syndrome (2 papers); breast carcinoma (1); celiac disease (1); colon cancer (1); follicular lymphoma (1); Galloway-Mowat syndrome (1); immune dysfunction (1); leukemia (1); liver cirrhosis (1); microphthalmia (1); prostate carcinoma (1); renal malformations (1); small lymphocytic-lymphomas (1).